PPP2R5A (protein phosphatase 2 regulatory subunit B'alpha)
Description:
The B regulatory subunit might modulate substrate selectivity and catalytic activity, and might also direct the localization of the catalytic enzyme to a particular subcellular compartment.
Synonyms: PR61A; B56A; B56alpha
Tractability: Small molecule: a structure with a bound ligand is known. Antibody: its Gene Ontology location is reachable by antibodies, with high confidence. PROTAC: ubiquitination databases record sites on it; its protein half-life has been measured; a small molecule that binds it is known.
Target class: Protein phosphatase regulatory subunit; Phosphatase; Enzyme; Protein Phosphatase
Chemical probes: OKADAIC ACID
Gene: Protein-coding gene on chromosome 1 (212,285,357 to 212,361,863, forward strand). Ensembl gene ENSG00000066027.
Subcellular location: Cytoplasm; Nucleus; Chromosome, centromere
Subcellular location (Human Protein Atlas): Cytosol
Pathways (Reactome):
Disease: APC truncation mutants have impaired AXIN binding; AXIN missense mutants destabilize the destruction complex; CTNNB1 S33 mutants aren't phosphorylated; CTNNB1 S37 mutants aren't phosphorylated; CTNNB1 S45 mutants aren't phosphorylated; CTNNB1 T41 mutants aren't phosphorylated; Signaling by GSK3beta mutants; Truncations of AMER1 destabilize the destruction complex
Signal Transduction: Beta-catenin phosphorylation cascade; Degradation of beta-catenin by the destruction complex; Disassembly of the destruction complex and recruitment of AXIN to the membrane; Negative regulation of MAPK pathway; PI5P, PP2A and IER3 Regulate PI3K/AKT Signaling; RAF activation; RHO GTPases Activate Formins
Cell Cycle: Amplification of signal from unattached kinetochores via a MAD2 inhibitory signal; EML4 and NUDC in mitotic spindle formation; Mitotic Prometaphase; Resolution of Sister Chromatid Cohesion; Separation of Sister Chromatids
Immune System: Co-inhibition by CTLA4; Co-stimulation by CD28; PKR-mediated signaling
Hemostasis: Platelet sensitization by LDL
Gene Ontology:
Molecular function: kinase binding; kinase inhibitor activity; protein binding; protein phosphatase activator activity; protein phosphatase regulator activity
Biological process: negative regulation of protein localization to plasma membrane; signal transduction
Cellular component: centrosome; cytoplasm; cytosol; nucleus; plasma membrane; protein phosphatase type 2A complex; Z disc; M band; chromosome, centromeric region
Genetic constraint (gnomAD): Loss-of-function variants: 20 observed, 37.38 expected, observed/expected ratio (o/e) 0.53, 90% interval 0.38 to 0.78. The upper end of that interval is the gene's LOEUF score, 0.78, which puts it in group 3 of 6, group 1 being the genes least tolerant of losing a copy. Missense variants: 332 observed, 396.81 expected, observed/expected ratio (o/e) 0.84, 90% interval 0.76 to 0.92. Synonymous variants: 157 observed, 138.01 expected, observed/expected ratio (o/e) 1.14, 90% interval 1 to 1.3.
Homologues: Orthologues: chimpanzee PPP2R5A (100% identical), macaque PPP2R5A (99% identical), dog PPP2R5A (99% identical), pig PPP2R5A (99% identical), guinea pig PPP2R5A (98% identical), rat Ppp2r5a (98% identical), mouse Ppp2r5a (98% identical), tropical clawed frog ppp2r5a (83% identical), zebrafish ppp2r5a (80% identical), rabbit PPP2R5A (77% identical), Drosophila melanogaster wdb (72% identical), Caenorhabditis elegans pptr-1 (64% identical), and 1 more. Paralogues in human: PPP2R5E (74% identical), PPP2R5B (70% identical), PPP2R5C (65% identical), PPP2R5D (63% identical).
Diseases named in the same sentence as PPP2R5A in open-access papers:
PPP2R5A is named in the same sentence as 33 diseases in open-access papers, as found by Europe PMC text mining. Sharing a sentence is not in itself a finding about the gene and the disease. The quoted sentences say what the papers report.
breast carcinoma (4 papers, 2014 to 2025). "However, in other cancer types (breast cancer and MDS), alternative splicing in PPP2R5A, MAP3K7, and IRAK4 has been linked to the activation of Akt and NF-κB pathway, TGF-β signaling, and inflammation pathway, respectively." (PMID 40694421, 2025). "PPP2R5A can activate the MAPK pathway, while the MAPK pathway is involved in promoting breast cancer cell invasion and non-small cell lung cancer cell invasion." (PMID 37081566, 2023).
oral cancer (3 papers, 2020 to 2025). "For instance, an investigation demonstrated that miR-218 directly targets protein phosphatase 2 regulatory subunit B’alpha (PPP2R5A), a tumor suppressor gene, influencing cancer progression and chemoresistance in oral cancer cells." (PMID 37888209, 2023).
colorectal cancer (2 papers, 2014 to 2022). A primary or metastatic malignant neoplasm that affects the colon or rectum. "We performed western blot assay to test PPP2R5A expression in control and eIF3a‐knockdown colorectal cancer cells." (PMID 35187743, 2022). "To investigate the exact regulatory role of PPP2R5A and the overall process of irinotecan‐activated ATM/ATR signalling, including phosphorylation and dephosphorylation, we exposed colorectal cancer cells to irinotecan for 1 h and then left the cells to recover for different time." (PMID 35187743, 2022).
leukaemia (2 papers, 2015 to 2023). "Notably, when we further assessed SF3B1K700E dependent alternative splicing of Ppp2r5a, which was reported to impair apoptosis via post-translational modification of BCL2 in leukaemia, we did not observe significant alternative 3’ss usage or mRNA expression of Ppp2r5a in KPC-Sf3b1K700E tumor cells." (PMID 37823551, 2023).
melanoma (2 papers, 2020 to 2024). A malignant, usually aggressive tumor composed of atypical, neoplastic melanocytes. "A reduction in the expression of PPP2R5A and PPP2R5C, the genes responsible for encoding B56α and B56γ, respectively, was observed in metastatic tissues of melanoma, resulting in the overexpression of C-MYC occurred and the suppression of oncogene-induced senescence." (PMID 38542160, 2024).
Arrhythmia (1 paper, 2020). Any cardiac rhythm other than the normal sinus rhythm. "Consistent with our research, some studies support PPP2R5A as a novel target for the treatment of arrhythmia." (PMID 33014188, 2020).
chronic lymphocytic leukaemia (1 paper, 2023). "Previous studies have shown that in chronic lymphocytic leukaemia (CLL) SF3B1K700E leads to missplicing of PPP2R5A, which in turn stabilizes c-Myc and thereby promotes aggressiveness of tumor cells." (PMID 37823551, 2023).
colon cancer (1 paper, 2021). "However, overexpression of both the wt and the R112L mutated version of PPP2R5A had a similar negative impact on colon cancer cell growth and did not alter CET treatment sensitivity." (PMID 34271981, 2021).
Influenza Infection (1 paper, 2020). "The risk gene PPP2R5A is mainly involved in Influenza Infection, protein localization to membrane, PID IGF1 PATHWAY, CTLA4 inhibitory signaling, Platelet activation, signaling and aggregation, and Hemostasis." (PMID 33014188, 2020).
Intellectual disability (1 paper, 2023). "Four mTOR-related genes associated with intracranial volume and intellectual disability, namely, PPP2R5A, PPP2R5C, AKT2, and MTOR, are among the top list of positively selected genes in the human lineage." (PMID 37789379, 2023).
lymphoma (1 paper, 2025). A malignant (clonal) proliferation of B- lymphocytes or T- lymphocytes which involves the lymph nodes, bone marrow and/or extranodal sites. "In 3 disease types — pancreatic ductal adenocarcinoma, UVM, and lymphoma — the MYC pathway is activated through alternative splicing in PPP2R5A or BRD9." (PMID 40694421, 2025).
pancreatic cancer (1 paper, 2023).
Parkinson disease (1 paper, 2023). A progressive degenerative disorder of the central nervous system characterized by loss of dopamine producing neurons in the substantia nigra and the presence of Lewy bodies in the substantia nigra and locus coeruleus. "The CREB5/CACNA1B/GNB4/PPP2R5A gene was found to be closely related to Parkinson’s disease in pathways of dopaminergic synapses." (PMID 37323142, 2023).
polycystic ovary syndrome (1 paper, 2021). A disorder that manifests as multiple cysts on the ovaries. "Ppp2r5a at Fmgq1 has been associated with polycystic ovary syndrome (PCOS) through pathway analysis of genes enriched in genome-wide association studies (GWAS)." (PMID 33723359, 2021).
tumor (25 papers, 2016 to 2025). "Collectively, these results suggest that SF3B1 K700E mutation leads to the aberrant splicing of PPP2R5A and the increased expression of c‐Myc, which leads to an enhanced Warburg effect and subsequent tumor growth in PDAC." (PMID 33932092, 2021). "Further mechanistic studies identified that the SF3B1 K700E mutation resulted in aberrant splicing of PPP2R5A and led to an increase in c‐Myc expression, which ultimately promoted the Warburg effect and tumor growth in PDAC." (PMID 33932092, 2021). "Loss of PPP2R5A function predicts tumor sensitivity to PARP inhibition due to impaired homologous recombination." (PMID 29100308, 2017). "Abnormality of PPP2R5A is often associated with many diseases, including several types of tumours." (PMID 35187743, 2022). "PPP2R5A was shown to be involved in the migration and invasion of a variety of tumour cells, suggesting its possible involvement in the inhibition of trophoblast invasion by CeO2NPs exposure." (PMID 37081566, 2023). "SF3B1K700E led to aberrant splicing of PPP2R5A, coupled with c‐Myc activation higher aerobic glycolysis rate and growth advantage of tumor cells." (PMID 33932092, 2021). "We also observed a recurrent mutation in the tumor suppressor protein phosphatase 2 regulatory subunit B'alpha (PPP2R5A; R112L) in 4 SR tumor models (BoC10, 32, 209, and 237)." (PMID 34271981, 2021). "Exonic deletions were detected in the PPP2R5A, FHIT, LRP1B, and OPCML tumor suppressor genes, as well as in genes implicated in cellular proliferation (CCNB1, ANAPC5, PIK3C2A) and DNA repair (SMARCA5)." (PMID 30836646, 2019). "Typical examples included known or putative tumor suppressors, such as NF1, DICER1, PML, PDS5A, MAP3K7, and PPP2R5A, in which SF3B1 mutation resulted in usage of alternative 3′ splice sites." (PMID 30194306, 2018). "Promoter methylation analysis revealed that PPP2R2B, and to some extent PPP2R3A and PPP2R5A are the only subunits predominantly methylated across multiple tumor types." (PMID 27557495, 2016). "PPP2R5A participates in a variety of tumour related signalling pathways." (PMID 37081566, 2023). "Taken together, aberrant PPP2R5A splicing induced by SF3B1 mutation might contribute to c‐Myc activation and subsequent glycolytic metabolism and tumor growth." (PMID 33932092, 2021). "AMPK (CAMKK2, CREBs, PPP2R5A/B, PPP2RC/D) and cAMP (BAD, PLN) pathways regulate energy balance and induce autophagy and apoptosis, inhibiting tumour cell growth." (PMID 41007296, 2025).
cancer (12 papers, 2014 to 2025). A tumor composed of atypical neoplastic, often pleomorphic cells that invade other tissues. "Increased expression of the miRNA’s that repress PPP2R5A (B56α) transcription, miR-338-5P and miR-218, were found to deplete expression of B56α expression in cancer." (PMID 36328247, 2022). "Some of the high scoring BioChIP-seq enrichment sites included genes that have been implicated in cancer metastases (DDR1, BMP4, and SMAD6), and cell cycle and survival (CDIP1 and PPP2R5A)." (PMID 36207293, 2022). "Among them, a few have been previously implicated in modulating drug sensitivity in other cancer types, including PPP2R2B, PPP2R2A, PPP2R5A, and PPP2R1A24,31,37." (PMID 33208750, 2020). "PPP2R5A is one of the regulatory subunits of protein phosphatase 2 A (PP2A) and plays an important role in regulating cancer development." (PMID 37081566, 2023).
PPP2R5A also shares sentences with these, for which no sentence is quoted: cardiac hypertrophy (2 papers); acute lymphoblastic leukemia (1); acute T cell leukemia (1); COVID-19 (1); endometrial cancer (1); endotoxemia (1); infection (1); liver cancer (1); lung carcinoma (1); lung squamous cell carcinoma (1); neuroblastoma (1); non-small cell lung carcinoma (1); pancreatic ductal adenocarcinoma (1); papilloma (1); pituitary tumor (1); skin papilloma (1); Ventricular arrhythmia (1).